SYT6 (synaptotagmin 6)
Description:
May be involved in Ca(2+)-dependent exocytosis of secretory vesicles through Ca(2+) and phospholipid binding to the C2 domain or may serve as Ca(2+) sensors in the process of vesicular trafficking and exocytosis. May mediate Ca(2+)-regulation of exocytosis in acrosomal reaction in sperm (By similarity).
Synonyms: SytVI
Tractability: Antibody: UniProt places it where antibodies can reach, with medium confidence; UniProt predicts a signal peptide or a membrane-spanning region; its Gene Ontology location is reachable by antibodies, with medium confidence. PROTAC: its protein half-life has been measured.
Gene: Protein-coding gene on chromosome 1 (114,089,291 to 114,153,880, reverse strand). Ensembl gene ENSG00000134207.
Subcellular location: Cytoplasmic vesicle, secretory vesicle, synaptic vesicle membrane; Membrane (Isoform 1); Cytoplasm, cytosol (Isoform 2); Cell membrane
Subcellular location (Human Protein Atlas): Vesicles
Gene Ontology:
Molecular function: calcium-dependent phospholipid binding; clathrin binding; syntaxin binding; calcium ion sensor activity; SNARE binding
Biological process: acrosomal vesicle exocytosis; chemical synaptic transmission; regulation of calcium ion-dependent exocytosis; vesicle-mediated transport
Cellular component: cytoplasmic side of plasma membrane; cytosol; exocytic vesicle; membrane; perinuclear endoplasmic reticulum; plasma membrane; synaptic vesicle membrane
Genetic constraint (gnomAD): Loss-of-function variants: 18 observed, 36.98 expected, observed/expected ratio (o/e) 0.49, 90% interval 0.34 to 0.72. The upper end of that interval is the gene's LOEUF score, 0.72, which puts it in group 2 of 6, group 1 being the genes least tolerant of losing a copy. Missense variants: 525 observed, 607.14 expected, observed/expected ratio (o/e) 0.86, 90% interval 0.8 to 0.93. Synonymous variants: 231 observed, 235.51 expected, observed/expected ratio (o/e) 0.98, 90% interval 0.88 to 1.09.
Homologues: Orthologues: macaque SYT6 (98% identical), mouse Syt6 (96% identical), guinea pig SYT6 (96% identical), pig SYT6 (96% identical), rat Syt6 (95% identical), chimpanzee SYT6 (82% identical), rabbit SYT6 (80% identical), dog SYT6 (79% identical), tropical clawed frog syt6 (77% identical), zebrafish syt6a (69% identical), zebrafish syt6b (66% identical). Paralogues in human: SYT10 (65% identical), SYT9 (56% identical), SYT3 (48% identical), SYT1 (32% identical), SYT5 (31% identical), SYT2 (30% identical), SYT7 (30% identical), SYT11 (29% identical), SYT17 (28% identical), SYT4 (27% identical), RPH3A (25% identical), SYT12 (25% identical), and 19 more.
Diseases named in the same sentence as SYT6 in open-access papers:
SYT6 is named in the same sentence as 7 diseases in open-access papers, as found by Europe PMC text mining. Sharing a sentence is not in itself a finding about the gene and the disease. The quoted sentences say what the papers report.
depression (1 paper, 2019). "Also, activity-dependent BDNF release via endocytic pathways can be regulated by syt6 and complexin, which is closely linked to depression." (PMID 31024237, 2019).
hyperlipidemia (1 paper, 2022). "This suggested hyperlipidemia might have a negative effect on the Syt6-modulated synaptic vesicle exocytosis." (PMID 35942128, 2022).
schizophrenia (1 paper, 2012). A major psychotic disorder characterized by abnormalities in the perception or expression of reality. "In our study, SYT6 was found to be downregulated in the left STG of schizophrenia patients." (PMID 22441714, 2012).
nervous system disease (1 paper, 2021). "As the offspring became older (16 months of age), we found that some genes of benefit to nervous system disease were activated, such as Lhx8, GPR88, RGS9, CD4, DRD2, RXRG, and Syt6, following the increase in the number of cholinergic and GABAergic neurons." (PMID 33819195, 2021). "In the present study, we found that some genes of benefit to nervous system disease were activated (such as Lhx8, GPR88, RGS9, CD4, DRD2, RXRG, and Syt6), following the increase in the number of cholinergic and GABAergic neurons in the HSHF-diet offspring." (PMID 33819195, 2021). "When the offspring grew older (16 months), we found that some genes of benefit against nervous system disease were activated, such as Lhx8, GPR88, RGS9, CD4, DRD2, RXRG, and Syt6, and the expression of cholinergic and GABAergic neurons biomarker protein increased." (PMID 33819195, 2021).
SYT6 also shares sentences with these, for which no sentence is quoted: COVID-19 (1 paper); Obesity (1); Parkinson disease (1).